RNU6-759P (RNA, U6 small nuclear 759, pseudogene)
Gene: Small nuclear RNA gene on chromosome 20 (35,647,328 to 35,647,430, reverse strand). Ensembl gene ENSG00000252549.
Homologues: Orthologues: chimpanzee U6 (97% identical), macaque U6 (85% identical), pig U6 (77% identical), rat U6 (68% identical). Paralogues in human: RNU6-42P (87% identical), RNU6-46P (86% identical), RNU6-12P (85% identical), RNU6-13P (85% identical), RNU6-16P (85% identical), RNU6-32P (85% identical), RNU6-33P (85% identical), RNU6-480P (85% identical), RNU6-536P (85% identical), RNU6-708P (85% identical), RNU6-1 (84% identical), RNU6-1011P (84% identical), and 1286 more.